MBP (myelin basic protein)
Diseases named in the same sentence as MBP in open-access papers (continued):
Sharing a sentence is not in itself a finding about the gene and the disease.
schizophrenia (continued). "Also we investigated associations between some immunological patterns and markers of inflammatory response (CRP, IL-2, IL-6, IL-10, the activity of LE and a1-PI, antibodies to S100B and MBP) with clinical symptoms in schizophrenia." (PMID 34025476, 2021). "Interestingly, the expression of myelin basic protein (MBP) is reduced in the hippocampus of a demyelination animal model of schizophrenia (Cumberland, Palliser, Rani, Walker, & Hirst, 2017)." (PMID 32363773, 2020). "A similar relationship was observed for the MBP-hydrolyzing activity of IgG in schizophrenia." (PMID 33008051, 2020). "Therefore, the purpose of this study was to investigate the characteristics of MBP proteolysis by serum polyclonal antibody (abzymes) of schizophrenia patients depending on the clinical features of the disease." (PMID 32851101, 2020). "Antibodies to MBP in the serum of patients with schizophrenia were found long ago." (PMID 32851101, 2020). "Hydrolysis of MBP by antibodies from patients with schizophrenia has already been shown." (PMID 33008051, 2020). "Moreover, abzymes hydrolyzing DNA and MBP was revealed in sera of patients with schizophrenia also demonstrating neuropsychiatric components." (PMID 31905713, 2019). "Futhermore, MBP mRNA is reduced in the visual cortex of patients with schizophrenia suggesting that it may contribute to the pathophysiology underlying changes in their visual perception." (PMID 25964736, 2015). "In addition, the differential expression of MBP in the entorhinal cortex in schizophrenia patients correlates to migrational disturbances of pre-alpha cell clusters leading to deficits in axonal myelination and disturbed connectivity during neurodevelopment." (PMID 22350622, 2012). "Thus, it is possible that deterioration in the white matter in the right temporo‐parietal region is responsible for impaired motor speed in schizophrenia and that MBP is a potentially important target molecule for drug discovery for treating cognitive impairment." (PMID 39133634, 2024). "Moreover, the downregulation of myelin-related and oligodendrocyte genes such as proteolipid protein 1 (PLP1), transferrin (TF), oligodendrocyte transcription factor 1 (OLIG1), and upregulation of myelin basic protein (MBP) were reported in the PFC of patients with schizophrenia." (PMID 36833173, 2023). "However, the same activating effect of Ca2+ ions was found in the hydrolysis of MBP by IgGs of schizophrenia patients, which suggests that Ca2+-dependent proteolytic antibodies to different proteins are formed in schizophrenia, and also that similar mechanisms generate them." (PMID 33008051, 2020). "Furthermore, the formation of Abs hydrolyzing MBP is indicated in schizophrenia." (PMID 32751323, 2020). "A decrease in MBP and PLP in schizophrenia has been reported in several gene expression and proteome studies." (PMID 40410588, 2025). "For example, in the entorhinal cortex of schizophrenia patients, decreased levels of CTR1 were shown to correlate with other Cu-dependent events, such as expression of myelin basic protein (MBP)." (PMID 39172219, 2025). "Previously, an increase in the level of myelin basic protein (MBP)-hydrolyzing activity of antibodies was shown in patients with a number of neurological and mental disorders, including schizophrenia." (PMID 37189796, 2023). "Catalytic antibodies hydrolyzing DNA, RNA and miRNA, histones, and myelin basic protein (MBP) have been described in schizophrenia." (PMID 35546942, 2022). "Abzymes hydrolyzing MBP were found detected in the blood sera of HIV-infected patients, as well as in the case of MS, SLE, and schizophrenia." (PMID 33435385, 2021). "It has previously been demonstrated that patients with schizophrenia have lower serum BDNF, MBP, and GFAP levels, but higher serum IL-6 and S100B." (PMID 34025476, 2021).
schizophrenia (continued). "However, the negative role of histone-hydrolyzing IgGs in schizophrenia may be associated with the catalytic cross-reactivity of anti-histone IgGs to MBP, similar to that for such antibodies in SLE and HIV-infected patients." (PMID 33008051, 2020). "MBP-hydrolyzing abzymes have been detected in the blood of patients with MS, SLE, schizophrenia, and HIV-infected patients." (PMID 33143355, 2020). "Several genes were validated in APA sperm that were associated with autism spectrum disorder (CACNA1H, CNTNAP2, GRIN1, SHANK2, SHANK3, ZNF804A), schizophrenia (TCF3, ZNF804A), and bipolar disorder (COMT, DRD4, GRIN1, MBP, PRKCZ, SHANK2, TRPM2, ZNF804A), and in APA blastocysts (CACNA1H)." (PMID 32610362, 2020). "According to a study of convergent functional genomics, among the most promising candidate genes known to play a role in the disorder are disrupted-in schizophrenia (DISC1), transcription factor 4 (TCF4), myelin basic protein (MBP) and heat-shock 70-kDa protein 1B (HSPA1B)." (PMID 25658856, 2015). "Also, a recent study revealed that the resveratrol application to the MK-801-induced mouse model of schizophrenia does not correct behavioral disorders or demyelination and even reduces MBP expression." (PMID 37131098, 2023). "However, in our study, the quantity of the peptides from the light chain variable domains in IgGs from patients with schizophrenia does not correlate with the proteolytic activity against MBP." (PMID 37431466, 2023). "Analysis of substrate specificity demonstrated that the IgGs of two different schizophrenia patients effectively hydrolyzed five histones and MBP, but did not hydrolyze other control proteins (human and bovine serum albumin, human milk lactoferrin, human lysozyme) under the same reaction conditions." (PMID 33008051, 2020). "Interestingly, other proteomic studies have reported a reduction of the palmitoylation of many proteins, such as vesicular glutamate transporter 1 (VGLUT1), the small GTPase Ras, and myelin basic protein (MBP), in the dorsolateral prefrontal cortex in schizophrenia patients." (PMID 29910712, 2018). "Notably, while variation was observed across the hiPSC lines, the significant effects in MBP+ iOLs were not driven by a few extreme cell lines but were instead representative of consistent group-level trends among hiPSC lines from patients with schizophrenia." (PMID 40819083, 2025). "In the context of the Th1/Th2 immune response, the negative correlation of MBP-hydrolyzing activity with IFN-γ levels may reflect a Th1/Th2 imbalance, with an increased Th2 response (or humoral immunity) occurring in schizophrenia." (PMID 37189796, 2023). "RT-PCR confirmed reductions of MBP, ACTB and TB10, but not MOG or SCG10, in schizophrenia." (PMID 22675524, 2012).
autoimmune disease (39 papers, 2009 to 2025). A disorder resulting from loss of function or tissue destruction of an organ or multiple organs, arising from humoral or cellular immune responses of the individual to their own tissue constituents. "Indeed, immunization against human MBP is associated with the occurrence of pre-activated T-lymphocytes specific to MBP, and several authors have described immune reactions and autoimmune diseases as consequences of T-lymphocytes remaining from former immunizations." (PMID 26526848, 2015). "Using our refined iTRA approach, we noticed that genes that have far fewer splice junctions in murine mTEC included those encoding homologs of known autoantibody targets in human autoimmune disease (such as PLP1, MBP, and CYP21A2)." (PMID 34649931, 2021). "According to previous data, anti-MBP auto-Abs from sera of patients with several autoimmune diseases can hydrolyze only MBP, while anti-histones abzymes can split only histones." (PMID 33435385, 2021). "A myelin sheath of axons contains myelin basic protein (MBP) playing an important role in the pathogenesis of autoimmune diseases." (PMID 33143355, 2020). "According to published data, anti-MBP antibodies from sera of patients with several autoimmune diseases can hydrolyze only MBP, while anti-histones Abs can only split histones." (PMID 33143355, 2020). "Nevertheless, there is long-standing evidence that MBP 82-100 can induce neuroinflammation in autoimmune diseases." (PMID 28446142, 2017). "Many variations of EAE are now available; for example, Lewis rats can develop monophasic or chronic EAE after injection of myelin basic protein (MBP), and this is a stable animal model to explore the mechanisms underlying CNS autoimmune diseases." (PMID 24782598, 2014). "Overall, our analysis of high and low affinity MBP Ac1-11 specific T cells reveals several important aspects concerning the onset of the autoimmune disease, EAE." (PMID 21437282, 2011). "ADEM is thought to be an autoimmune disease in which it is theorized that autoimmune constituents attack myelin components such as myelin basic protein, proteolipid protein, and myelin oligodendrocyte protein leading to demyelination and diffuse white matter changes." (PMID 40729276, 2024). "The fourth cluster, the most pronounced in yellow, includes keywords “regulatory T-cells”, “myelin basic protein”, “dendritic cells”, and “autoimmune diseases”, indicating an exploration at the juncture of immunology and neuroscience, with a particular emphasis on autoimmune disease research." (PMID 39611149, 2024). "MS is considered to be a predominantly T cell-mediated autoimmune disease, directed toward various myelin-derived antigens, including myelin basic protein (MBP), proteolipid protein (PLP), myelin oligodendrocyte glycoprotein (MOG), and αB-crystallin, that are expressed in the CNS." (PMID 33679769, 2021). "Thus, in contrast to non-autoimmune mice, in Th mice, the concentration of antibodies against DNA, MBP, and MOG increases in time, as in the case of other animals predisposed to the development of spontaneous autoimmune diseases." (PMID 33595783, 2021). "Some HMGs, such as MBP, an immunodominant epitope of myelin basic protein that binds to the major histocompatibility complex haplotype HLA-DR2, are widely implicated in the pathogenesis of autoimmune diseases." (PMID 31001336, 2019). "In an attempt to explore whether this approach is also applicable to prevention of autoimmune diseases, syngeneic DCs were loaded with myelin basic protein (MBP), an autoantigen derived from the brain, incubated with MMC and then injected into mice." (PMID 27131971, 2016). "Thus, 1,25(OH)2D3 administration impaired the induction of CNS autoimmune disease in this model, likely by limiting the access of MBP-reactive CD4+ T cells to the CNS." (PMID 26635791, 2015). "MBP-primed Th2 cells have been shown to be beneficial in autoimmune diseases like MS." (PMID 24575330, 2013).
autoimmune disease (continued). "Myelin basic protein (MBP) peptide 1–9 was recognized by auto-reactive CD4 T cells and prevented the induction of an autoimmune disease." (PMID 28455817, 2017). "MS is widely considered to be an autoimmune disease due primarily to CD4+ T-cell mediated immune responses to the major myelin proteins, myelin basic proteins (MBP) and proteolipid proteins (PLP)." (PMID 26295036, 2015). "Still, our data shed light on the regulatory effect that PADI4 inhibitors could have on citrullination of proteins, including β-actin, enolase and myelin basic protein (MBP) 4,47,48, that are commonly citrullinated in autoimmune diseases." (PMID 38321148, 2024). "One study identified that Golli-MBP (human Golli-myelin basic protein) was suspected to play a role in the etiology of autoimmune diseases and the gene expression ratio of IFN-γ/IL-4, and increased Golli-MBP was related to a lower ratio of IFN-γ/IL-4 in OLP patients." (PMID 31181785, 2019). "Since free histones are pernicious proteins, antibodies–ABZs against five histones, MBP, and DNA could have a negative role in the pathogenesis of MS and probably other various autoimmune diseases." (PMID 36289924, 2022). "Anti-H2a, anti-H2b, and anti-MBP abzymes are unpredictable examples of IgGs possessing not only cross-complexation but also catalytic cross-reactivity, which may be a common phenomenon for such abzymes in patients with different autoimmune diseases." (PMID 33143355, 2020).
demyelinating disease (37 papers, 2008 to 2026). A broad group of disorders that affect the myelin sheaths that cover the neurons. "This pattern of MBP staining loss is similar to that found in demyelinating diseases and this finding suggests the reorganization of NaChs at demyelinated sites as a pulpal pain mechanism." (PMID 18426592, 2008). "However, many current proof-of-concept studies for replacement therapy for demyelinating diseases are performed in congenitally hypomyelinated shiverer mice with a partial deletion in the myelin basic protein (MBP)-encoding gene." (PMID 38475854, 2024). "Myelin basic protein (MBP) is a key structural component of central nervous system myelin and a clinically relevant molecule in demyelinating disorders; however, to the best of our knowledge, its Raman signature in solution has not been reported." (PMID 42188489, 2026). "Other markers of neuronal damage, such as CNS myelin basic protein (MBP), can indicate demyelinating diseases such as MS or acute demyelinating encephalomyelitis (ADEM)." (PMID 40310164, 2025). "Particularly, autoantibodies directed against MBP (myelin basic protein) and/or MOG (myelin oligodendrocyte glycoprotein) are implicated in the pathogenesis of MS and other demyelinating diseases." (PMID 39654365, 2024). "The stability of the MDL, the condition of MBP within it, and the post-natal myelinating machinery should be taken into account when it comes to understanding and possibly treating demyelinating diseases." (PMID 28694532, 2017). "There are also extensive studies demonstrating immune-activating effect of MBP on immune system during demyelinating disease." (PMID 25255088, 2014). "TPA, a serine protease and a well-recognized thrombolytic agent, is considered to be involved in demyelinating diseases by degrading myelin basic protein (MBP) and contributing to excitotoxic neuronal death by activating microglia." (PMID 21246060, 2010). "Studies have shown that immune responses triggered by vaccine components may generate antibodies against MBP, leading to autoimmune-mediated demyelinating disorders such as postvaccinal encephalomyelitis in a subset of recipients." (PMID 41441337, 2025). "This might entail immunizing mice with myelin basic protein followed by induction of demyelinating disease by oral gavage with Staphylococcal enterotoxin type A and with increasing concentrations of abrin toxin." (PMID 39727963, 2024). "Circulating levels of MBP increase after brain damage or demyelinating diseases." (PMID 38389906, 2024). "For patients with demyelinating disease, as indicated by imaging results, CSF should be examined for anti-aquaporin-4 antibody, anti-myelin oligodendrocyte glycoprotein antibody, anti-myelin basic protein antibody, and oligoclonal bands to further clarify the diagnosis." (PMID 36523348, 2022). "Inflammatory responses against MBP, MOG and MAG are known to cause demyelinating diseases." (PMID 32000863, 2020). "In addition, increase in CSF IgG, γ-globulin, and possibly in myelin basic protein (MBP) similar to that observed in demyelinating diseases have been reported in DM1 patients." (PMID 28473756, 2017). "Myelin basic protein (MBP) is a major component of the myelin sheath of CNS neurons and may play a central role in demyelinating diseases such as MS." (PMID 28413712, 2017). "More detailed insights into the MBP synthesis pathway are important for a better understanding of the myelination process and may foster the development of remyelination therapies for demyelinating diseases." (PMID 24098271, 2013). "Moreover, PURA has been demonstrated to regulate MBP gene transcription and, under particular immunosuppressive conditions, into the demyelinating disease named progressive multifocal leukoencephalopathy, which precisely consists in the degeneration of the oligodendroglial cells." (PMID 34063504, 2021).
demyelinating disease (continued). "Myelin basic protein (MBP), a component of the myelin sheath, in the cerebrospinal fluid (CSF) has been suggested as a biomarker for white matter damage in demyelinating diseases." (PMID 39133634, 2024). "As fibrinogen has been shown to be necessary for OPC differentiation and myelination in demyelinating diseases, but not after ischemic damage, we investigated fibrinogen deposition related to MBP+ OL distribution after ischemia." (PMID 36756722, 2023). "The mechanisms of myelin breakdown in MS are not clearly established but degradation of MBP has been thought to be the initial step in the breakdown of myelin in demyelinating diseases." (PMID 23635033, 2013). "Thus, while the cervical cord showed significant downregulation of CNPase and MOG only but not MBP, the thoracic region of the spinal cord showed significant downregulation of all three myelin proteins at the peak of demyelinating disease." (PMID 39292341, 2025). "Finally, specific antibodies (AQP4/MOG/MBP) did not detect any signs of demyelinating diseases in the central nervous system (CNS)." (PMID 34791569, 2022). "We suggest that increased mRNA levels of ARE-containing myelin proteins (MBP, MOBP) resulting from EXOSC8 deficiency initiate a cascade of downstream events, and the disturbed balance between ARE and non-ARE myelin components results in demyelinating disease." (PMID 24989451, 2014). "In this study we have shown that mice with HSV-IL-2-induced and MOG-induced demyelinating diseases demonstrated a similar pattern and distribution of demyelination in their brain, spinal cord, and optic nerves, while no demyelination was detected in the optic nerves of MBP- and PLP-injected mice." (PMID 36817487, 2023).